TBC1D12 (TBC1 domain family member 12)
Description:
RAB11A-binding protein that plays a role in neurite outgrowth.
Synonyms: KIAA0608
Tractability: PROTAC: its protein half-life has been measured.
Gene: Protein-coding gene on chromosome 10 (94,402,451 to 94,536,332, forward strand). Ensembl gene ENSG00000108239.
Subcellular location: Endosome
Subcellular location (Human Protein Atlas): Nuclear speckles; Nucleoplasm
Gene Ontology:
Molecular function: GTPase activator activity; enzyme binding
Biological process: regulation of autophagosome assembly; vesicle-mediated transport
Cellular component: endosome; autophagosome; recycling endosome; cytoplasmic vesicle; vacuole
Genetic constraint (gnomAD): Loss-of-function variants: 36 observed, 54.36 expected, observed/expected ratio (o/e) 0.66, 90% interval 0.51 to 0.88. The synonymous counts are far from expectation, so gnomAD's model fits this gene poorly and the ratio says little. Missense variants: 872 observed, 746.1 expected, observed/expected ratio (o/e) 1.17, 90% interval 1.11 to 1.24. Synonymous variants: 372 observed, 300.01 expected, observed/expected ratio (o/e) 1.24, 90% interval 1.14 to 1.35.
Homologues: Orthologues: chimpanzee TBC1D12 (99% identical), macaque TBC1D12 (95% identical), dog TBC1D12 (87% identical), pig TBC1D12 (86% identical), guinea pig TBC1D12 (77% identical), mouse Tbc1d12 (77% identical), rat Tbc1d12 (77% identical), rabbit TBC1D12 (62% identical), tropical clawed frog tbc1d12 (59% identical), zebrafish tbc1d12b (50% identical). Paralogues in human: TBC1D14 (45% identical), TBCK (15% identical), TBC1D1 (14% identical), TBC1D4 (14% identical), TBC1D2B (14% identical), USP6NL (14% identical), TBC1D2 (13% identical), RABGAP1 (13% identical), RABGAP1L (13% identical), TBC1D9 (13% identical), TBC1D16 (12% identical), TBC1D10B (12% identical), and 33 more.
Diseases named in the same sentence as TBC1D12 in open-access papers:
TBC1D12 is named in the same sentence as 9 diseases in open-access papers, as found by Europe PMC text mining. Sharing a sentence is not in itself a finding about the gene and the disease. The quoted sentences say what the papers report.
asthma (1 paper, 2023). "RN4RL1, found on vagal sensory neurons, likely contributes to airway hyperreactivity and neuronal hypothesis of asthma pathogenesis, similar to TBC1D12, the down-regulation of which may result in airway neurite sprouting, another feature of airway remodeling." (PMID 36835202, 2023).
bladder cancer (1 paper, 2023). "Mutations at specific hotspots in non-coding regions of ADGRG6, PLEKHS1, WDR74, TBC1D12 and LEPROTL1 frequently occur in bladder cancer (BC)." (PMID 36658180, 2023).
muscular dystrophy (1 paper, 2021). Muscular dystrophy (MD) refers to a group of more than 30 genetic diseases characterized by progressive weakness and degeneration of the skeletal muscles that control movement. "Upregulated in both datasets was Tbc1d12 involved in increasing glucose uptake, whereas the shared downregulated genes included Ptp4a3, the downregulation of which increases expression of ECM genes, and Fbxo40, the downregulation of which has been observed in muscular dystrophy." (PMID 34502375, 2021).
cancer (5 papers, 2016 to 2023). A tumor composed of atypical neoplastic, often pleomorphic cells that invade other tissues. "Although recurrently promoter or UTR mutations for PLEKHS1 and TBC1D12 have been reported in several cancers, the functional role of these genes in tumorigenesis still remains uncharacterized." (PMID 30755618, 2019). "Other DVPs for solid cancers were annotated to genes related to bladder (TBC1D12), breast (AQP12B) or lung, prostate and colorectal (GFI1) cancers." (PMID 33632303, 2021).
tumor (3 papers, 2020 to 2023). "We observed a higher mRNA expression of TBC1D10C, TBC1D4, TBC1D12, TBCK, TBC1D5, TBC1D30 and a lower expression of TBC1D24 in patients with tumor compared with tumor free patients." (PMID 33194704, 2020). "Interestingly, we also discovered three genes (TBC1D12, KERA, and TUBA3D) that have not been previously associated with tumor-related autophagy." (PMID 37628602, 2023). "Lastly, three genes (TBC1D12, KERA, and TUBA3D) that contribute to tumor clustering in groups “0” and “1” have not been previously associated with the tumor-related autophagy process." (PMID 37628602, 2023).
TBC1D12 also shares sentences with these, for which no sentence is quoted: breast carcinoma (2 papers); basal cell carcinoma (1); infection (1); skin cutaneous melanoma (1).